THY1 (Thy-1 cell surface antigen)
Diseases named in the same sentence as THY1 in open-access papers (continued):
Sharing a sentence is not in itself a finding about the gene and the disease.
infection (continued). "To highlight the contribution of each/combinations of reprogramming factors, and possible suppressive effects of each capability to repress Thy1, we infected MEF with individual reprogramming factors or combinations of factors and assessed Thy1 at day 12 after infection." (PMID 22619682, 2012). "MEFs which retained Thy-1 expression after 4F infection did not induce miR-135b and retained expression of ECM-associated genes, and had a more limited, multipotent MSC-like phenotype compared to the truly pluripotent Thy-1- iPSCs." (PMID 30859102, 2019). "On the other hand, THY-1 may not be required for infection of all cell types; instead, it functions in a cell type dependent manner." (PMID 26147640, 2015). "Notably, depletion of T cells systemically and in the ear using an anti-Thy1 antibody did not increase virus titers in the ear through day 9 post infection or allow detection of VACV in the ovaries (data not shown)." (PMID 22102816, 2011). "However, by 4 months post-challenge, the phenotypic differences between the Thy1+ liver NK cell population in control and vaccinia virus-infected mice observed during the acute phase of infection was no longer apparent." (PMID 21829360, 2011). "Our EdU incorporation experiments established that the expansion in total NK cell numbers, and Thy1+ NK cells in particular, is driven by in situ proliferation of Thy1+ NK cells during the first week of infection, not the accumulation of effector cells migrating from peripheral sites." (PMID 21829360, 2011). "However, delayed wound healing in mice lacking Thy-1, might have severe consequences for the individual since infections occur during the initial stages of the healing process." (PMID 36293394, 2022). "Moreover, neutrophils help maintain the damaged area free of pathogens, and delayed arrival of these cells due to Thy-1 absence would favor infection of the area, which could then favor a chronic non-healing wound process." (PMID 36293394, 2022). "THY1 (thy-1 cell surface antigen) and CFP (complement factor properdin), which showed changes of less than 2-fold in the microarray results, and HIRF (HPS infection related factor), which was not annotated in the analysis of GO, were also selected for QPCR confirmation." (PMID 19196461, 2009).
kidney disease (6 papers, 2013 to 2020). "Recently, PAI-1 has emerged as a powerful fibrogenic mediator in kidney diseases, including diabetic nephropathy and anti-Thy-1-antibody-mediated glomerulonephritis." (PMID 27258009, 2016). "In addition, the role of S1P in a chronic model of kidney disease has been explored in a rat model of anti‐Thy1‐induced chronic progressive glomerulosclerosis." (PMID 24744854, 2013).
neurodegenerative disease (3 papers, 2012 to 2017). A disorder of the central nervous system characterized by gradual and progressive loss of neural tissue and neurologic function. "Therefore, our results support Thy-1 and β3 Integrin/Syndecan-4 as potential targets for the clinical management of neurodegenerative diseases involving inflammatory processes." (PMID 28962574, 2017). "Although we did not observe neuron loss in the right BLA, it is nonetheless possible that functional changes occurred in Thy1 and PARV neurons in right BLA, given that neurons can be dysfunctional after brain injury or in neurodegenerative diseases, in the absence of or prior to overt neuron loss." (PMID 27766068, 2016).
immune system diseases (2 papers, 2018 to 2022). "DEGs that enriched to “immune system diseases” played critical roles in cell-matrix communication (THY1, LVRN, LUM, TIMP3, SPOCK1, LGALS3BP, FAT2, and SERPINE2) as well as inflammation (IL1R2, CD22, PTGES, TNFSF10, IL2RB, C3, SERPING1, and IL-17RE)." (PMID 30131724, 2018).
metabolic disorder (2 papers, 2019 to 2022). "It would also be interesting to investigate whether THY1 acts as a linker between ER stress and metabolic disorders in NAFLD." (PMID 36034446, 2022).
neurological diseases (2 papers, 2019 to 2026). "At the same time, our data indicate the role of Thy1 in the functioning of the striatal targets of gabapentin, the critical therapeutic agent used in the treatment of some neurological disorders." (PMID 41542890, 2026).
adenocarcinoma (1 paper, 2015). A common cancer characterized by the presence of malignant glandular cells. "In HCMV- infected adenocarcinoma HS-578T cells, gB also colocalized with THY-1." (PMID 26147640, 2015).
neurodevelopmental disorder (1 paper, 2015). A behavioral and cognitive disorder with onset during the developmental period that involves impaired or aberrant development of intellectual, motor, or social functions. "Thy1 knockout mice show impaired LTP in dentate gyrus and behavioral abnormalities such as impaired social transmission of food preference that are consistent with a critical function for this locus in neurodevelopment and neurodevelopmental disorders." (PMID 25849048, 2015).
psychiatric diseases (1 paper, 2020). "Thus, the decreased suppression of Thy1- neurons by GABAARs following CSDS may also participate in stress-related psychiatric diseases, while the exact neuron type needs to be identified in future study." (PMID 32362809, 2020).
THY1 also shares sentences with these, for which no sentence is quoted: idiopathic pulmonary fibrosis (13 papers); osteosarcoma (10); colorectal cancer (8); esophageal squamous cell carcinoma (8); acute myeloid leukemia (6); myocardial infarction (6); hepatoblastoma (5); keloid (5); bladder cancer (4); COVID-19 (4); intrahepatic cholangiocarcinoma (4); Lipedema (4); liver cirrhosis (4); non-small cell lung carcinoma (4); ulcerative colitis (4); autoimmune disease (3); B cell lymphomas (3); chondrosarcoma (3); chronic kidney disease (3); Crohn disease (3); gallbladder cancer (3); insulinoma (3); malignant glioma (3); multiple myeloma (3); osteoporosis (3); sarcoma (3); acute lymphoblastic leukemia (2); adrenal carcinoma (2); atherosclerosis (2); breast (2).
A further 153 diseases each share a sentence with THY1 in 2 papers or fewer.